IL4 (interleukin 4)
Diseases named in the same sentence as IL4 in open-access papers (continued):
Sharing a sentence is not in itself a finding about the gene and the disease.
hematoma (8 papers, 2014 to 2023). A hematoma is a collection of blood from a vascular structure into an extravascular space. "In terms of effects, they both support that IL-4 promotes hematoma resolution by targeting microglia." (PMID 36970539, 2023). "A small number of studies have demonstrated that IL-4 treatment after ICH promotes hematoma absorption, relieves neuroinflammation, and enhances neural functional recovery through the STAT6 signaling pathway." (PMID 36970539, 2023). "Exploratory factor analysis indicated two major underlying immunological processes expressed by the cytokines in both blood and hematoma fluid, but with a different pattern and particularly regarding the cytokines IL-13, IL-6, IL-4 and TNF-α." (PMID 24587250, 2014). "We found that IL-4 could significantly decrease the iNOS+/Iba 1+ cells (P < 0.05; n = 3) surrounding the hematoma at 3 days after ICH." (PMID 27013935, 2016). "Results from the two exploratory factor analysis models indicated a different underlying cytokine pattern in venous blood compared with hematoma fluid samples, which seemed especially so for the pro-inflammatory cytokines IL-6 and TNF-α and the anti-inflammatory cytokines IL-4 and IL-13." (PMID 24587250, 2014). "In the earlier prospective cohort study of these two researchers on 57 patients, an association between increased hematoma fluid (but not serum) of a panel of biomarkers considered an anti-inflammatory index (IL-4, IL-5, IL-10, IL-13, IL-1 RA) and a reduced risk of recurrence was indicated." (PMID 37510193, 2023). "Recently, IL-4/STAT6 signaling accelerated microglia-and macrophage-mediated hematoma clearance and improved neurofunctional recovery following ICH in blood and collagenase injection models." (PMID 36439158, 2022). "In particular, the cytokines IL-13, IL-6, IL-4 and TNF- α exhibited differences in loadings between an exploratory factor analysis from blood and hematoma samples." (PMID 24587250, 2014). "The limited available data indicates that IL-4, as an anti-inflammatory factor, may induce the differentiation of anti-inflammatory microglia (also known as M2 microglia) through the STAT6 signaling pathway and mediate the phagocytosis of hematoma components." (PMID 36970539, 2023). "Since the cytokines IL-13, IL-6, IL-4 and TNF-α in particular displayed a different loading pattern in blood compared to hematoma fluid samples, they could play a different role in the local inflammatory response in the hematoma compared with the systemic response assessed in blood samples." (PMID 24587250, 2014).
Hepatic steatosis (8 papers, 2015 to 2025). Steatosis is a term used to denote lipid accumulation within hepatocytes. "A differential expression of IL-13, G-CSF, CCL11, IL-6 and IL-4 among patients at different stages of hepatic steatosis, highlighted a possible role of an inflammatory response in the development of hepatic steatosis and fibrosis in CHB patients." (PMID 36544761, 2022). "Our results showed a positive relation between the degree of hepatic steatosis and the expression profile of IL-4, IL-47, and CD163." (PMID 33906302, 2021). "While PPARγ, rather than PPARδ, is essential for initiating the metabolic shift in response to IL-4, the deletion of either isoform has been demonstrated to hinder IL-4-triggered alternative macrophage activation, leading to insulin resistance and the development of hepatic steatosis." (PMID 40977736, 2025). "Additionally, IL-4 expression in iNKT cells was lower in diabetic mice (p < 0.01), correlating with liver steatosis and inflammation." (PMID 40362271, 2025). "In addition, there is an increased expression of IL-4 in higher degrees of hepatic steatosis." (PMID 33906302, 2021). "Therefore, IL-4 may have dual roles in energy metabolism: on one hand, exerting protective function to inhibit lipid accumulation and promote catabolic efficiency; while on the other, leading to hepatic steatosis by promoting FFAs release from adipocytes into circulation." (PMID 31427606, 2019).
Hyperinsulinemia (8 papers, 2013 to 2025). An increased concentration of insulin in the blood. "The present study showed that the HF diet induced an increase of TNF-α and IL-6 pro-inflammatory cytokines plasma level and a decrease of IL-4 and IL-10 anti-inflammatory cytokines plasma level, associated with hyperinsulinemia and a high HOMA-IR index." (PMID 31091691, 2019). "Compared to a reference bottlenose dolphin without metabolic perturbations, the current study identified activated cytokine gene expression, including TGF-β, TNF-α, IFN-γ, IL-18, IL-13, IL-10, and IL-4 in the liver or spleen of a geriatric bottlenose dolphin with hyperinsulinemia." (PMID 24101915, 2013). "Metformin and hyperinsulinemia changed the expression of extracellular proteins (e.g. metformin: CTSL, EGFR, IL5, KLK3; insulin: IL4, IL15, PGC, SORL1)." (PMID 33690729, 2021). "Due to the pro-inflammatory nature of hyperinsulinemia, it is not surprising that corresponding anti-inflammatory cytokines, IL-4, IL-10, IL-13, and TGF-β, would also be upregulated in an effort to control the inflammation." (PMID 24101915, 2013).
interstitial lung disease (8 papers, 2009 to 2025). A diverse group of lung diseases that affect the lung parenchyma. "High IL-7 levels were characteristic of SSc-associated interstitial lung disease (ILD) and, in addition, when compared with ILD-negative SSc patients, ILD-positive SSc patients revealed higher IL-4, IL-6, IL-8, and CCL2 (MCP-1) BALF levels." (PMID 19615053, 2009). "SSc patients had higher serum levels of both IL-4 and IL-21 compared to HCs, and the serum levels of these cytokines were correlated with a reduction in the diffusion lung capacity for carbon monoxide (DLco) and the radiological extension of interstitial lung disease (ILD) in SSc patients." (PMID 37763102, 2023).
intracerebral hemorrhage (8 papers, 2016 to 2024). A cerebrovascular disorder characterized by bleeding into one or both cerebral hemispheres including the basal ganglia and the cerebral cortex. "Here, we investigated whether intracerebral administration of interleukin-4 (IL-4) at an early stage could affect the activation of microglia/macrophage and the corresponding outcome after intracerebral hemorrhage (ICH)." (PMID 27013935, 2016). "Early intracerebral injection of IL-4 potentially promotes neuro-functional recovery, probably through enhancing the activation of microglia M2 (protective) phenotype and inhibiting the activation of M1 (injurious/toxic) phenotype in patients with intracerebral hemorrhage." (PMID 35955921, 2022). "Metformin downregulated the expression levels of inflammatory cytokines (IL-1β, IL-4, and IL-6 and TNF-α) in intracerebral hemorrhage model rats." (PMID 32831980, 2020). "Only at P1 did IL-4 increase the protease activated receptor 1 (PAR-1/F2r), which is interesting because it is up-regulated in mouse microglia after intracerebral hemorrhage and contributes to edema, pro-inflammatory cytokine production and neuron death." (PMID 30524242, 2018). "Furthermore, administration of IL-4, a well-known anti-inflammatory cytokine and potent inducer of M2 microglia polarization, was shown to enhance M2 microglial polarization and improve functional and neurobehavioral outcomes following focal cerebral ischemia and intracerebral hemorrhage." (PMID 29849895, 2018). "Interleukin-4 (IL-4) serves as a canonical activator of signal transducer and activator of transcription 6 (STAT6), and exogenous IL-4 administration has been shown to activate STAT6 and enhance erythrophagocytosis in intracerebral hemorrhage (ICH)." (PMID 39660125, 2024). "IL-4 may partially promote M2 microglia/macrophage polarization through the JAK1/STAT6 pathway, therefore reducing neuroinflammation after intracerebral hemorrhage." (PMID 35204186, 2022).
Myocardial fibrosis (8 papers, 2013 to 2025). "IL-4 promotes the expression of interstitial collagen content, leading to enhanced myocardial fibrosis and cardiac failure." (PMID 41272035, 2025). "It has been verified in both clinical cohort and animal model studies that the Th2 cytokine IL-4 participates in HF progression by promoting myocardial fibrosis." (PMID 35687056, 2022). "In addition to this, IL-4 can promote myocardial fibrosis by upregulating collagen genes and stimulating collagen production in mouse CFs, mediated through the signal transducers and activators of transcription 6 (STAT6) signaling pathway." (PMID 40881586, 2025). "Moreover, high concentrations of IL-4 can induce macrophage polarization toward an M2 phenotype that inhibits inflammation and promotes scarring, a process that has been shown to promote the process of myocardial fibrosis." (PMID 40881586, 2025). "However, production of IL-4 by ILC2s and T cells persistent in the end of recovery stage may also promote myocardial fibrosis." (PMID 32431711, 2020). "CD4+ Th2-type immune responses, mediated by IL-4, are believed to drive fibrotic process and recent study revealed that TNF-α-Secreting B Cells may contribute to myocardial fibrosis in DCM." (PMID 24023968, 2013).
pertussis (8 papers, 2009 to 2024). A contagious bacterial respiratory infection caused by Bordetella pertussis. "Three inflammatory cytokines were found to have a causal relationship with pertussis: IL-4 (OR = 0.3688, 95% CI = 0.16571–0.8208, P = .0145418), IL-18R1 (OR = 1.2757, 95% CI = 1.0499–1.5501, P = .0143), and FGF-21 (OR = 2.0747, 95% CI = 1.0669–4.0341, P = .03147)." (PMID 39612418, 2024). "Although IL-4, IL-18R1, and FGF-21 were found to have direct causal relationships with pertussis, the 2-step MR analysis showed that inflammatory cytokines do not mediate the effect of immune cells on pertussis." (PMID 39612418, 2024). "The acellular pertussis vaccines induced a mixed cytokine profile showed elevated IFN-γ production (associated with IL-2), low IL-4, and more abundant IL-5 production." (PMID 37574522, 2023). "One-month post-primary pertussis vaccination, infants from vaccinated pregnancies still had lower IL-10 responses to B. pertussis, as well as lower IL-4." (PMID 34649076, 2021). "This study also identified 3 inflammatory cytokines (IL-4, IL-18R1, and FGF-21) with causal relationships with pertussis, suggesting that these cytokines may play direct roles in the development of the disease." (PMID 39612418, 2024). "Additionally, 3 inflammatory cytokines – IL-4, IL-18R1, and FGF-21 – show a causal relationship with pertussis." (PMID 39612418, 2024). "While the IL-4 and IFN-γ responses to the pool of pertussis antigens were stable, the IL-17 response in the DTwP primed group appeared to be transient after Tdap boost, and decreased to baseline level at M10, that is, 6 months post boost." (PMID 33815369, 2021). "No matter if IL-4 was measurable or not, anti-pertussis antibodies were significantly induced in mice immunized with each of the three recombinant proteins." (PMID 20040101, 2009).
Pleural effusion (8 papers, 2012 to 2026). The presence of an excessive amount of fluid in the pleural cavity. "The χ 2 text and Mann-Whitney U Test analysis indicated that ESR, CD4+ T cells, NK cells, IL-4, duration of fever, and pleural effusion were significant predictors of NP in children with MPP (P < 0.05)." (PMID 41695751, 2026). "In our study, TB and TP patients secreted high antigen specific IFN-γ level detected by ELISPOT (SFCs>110), and plasma level of IFN-γ were markedly increased in the pleural effusion of TP patients but with low IL-4 level." (PMID 22719887, 2012).
prurigo nodularis (8 papers, 2020 to 2025). Prurigonodularis (PN) is a skin disease in which hard crusty lumps are formed on the skin that itches intensely. "IL-31, a cytokine associated with itching and the pathophysiology of prurigo nodularis, is crucial in T-helper 2 skin inflammation by promoting the production of IL-4 and IL-13." (PMID 41110231, 2025). "Type 1 helper T cells (Th1), IL-4/IL-13, and Th2 cytokines interferone-γ are assumed to be factors inducing the spongiotic epidermal changes in prurigo nodularis in the course of disease progression." (PMID 33182351, 2020).
psoriasis vulgaris (8 papers, 2016 to 2025). Plaque psoriasis is the most common presentation of psoriasis. "Pre-selected SNP sets were associated with psoriasis vulgaris analysis, which was used to identify four SNP-associated targeted therapy efficiencies: IL1β (rs1143633), IL4 (IL13) (rs20541), IL23R (rs2201841), and TNFα (rs1800629) genes." (PMID 33383665, 2020). "The pooled analyses suggest that levels of IFN-γ, IL-17, IL-23, and TNF-α are significantly elevated and that levels of IL-4 and IL-10 are significantly decreased in sera of patients with psoriasis vulgaris of blood-heat syndrome." (PMID 27274756, 2016). "Studies found that the increased Th2 and Th17 immune response may play a role in EP pathogenesis, endorsed by the higher serum level of interleukin (IL)-13, IL-4, IL-6 and IL-10 in EP patients than patients with plaque psoriasis." (PMID 34970217, 2021). "In the present study as well, GM-CSF and IL-4 enhanced OSM expression in isolated human monocytes, and there is a trend toward higher CCL2 expression in the skin lesions of AD and psoriasis vulgaris." (PMID 38035099, 2023). "A study showed that patients with blood-heat syndrome of psoriasis vulgaris had substantially elevated levels of interferon-gamma, IL-17, IL-23, and TNF-α and significantly decreased levels of IL-4 and IL-10." (PMID 32843084, 2020). "Meta-analysis of the results for all markers, including IFN-γ, IL-4, IL-17, IL-23, IL-6, TNF-α, and IL-10, for subjects with psoriasis vulgaris of blood-heat syndrome revealed significant between-study heterogeneity (I2 > 75%) with random-effects modeling." (PMID 27274756, 2016). "In summary, patients with psoriasis vulgaris of blood-heat syndrome show significantly elevated levels of IFN-γ, IL-17, IL-23, and TNF-α and decreased levels of IL-4 and IL-10." (PMID 27274756, 2016). "We performed a systematic review and meta-analysis to determine whether seven well-known immunological serum markers (IFN-γ, IL-4, IL-17, IL-23, IL-6, TNF-α, and IL-10) are elevated or decreased in patients with psoriasis vulgaris of blood-heat syndrome compared with controls." (PMID 27274756, 2016).
sensitization (8 papers, 2013 to 2023). "Th2 cells produce IL-4, IL-5, IL-6, and IL-10, mediate humoral immunity, and are closely associated with the development of hypersensitivity reactions." (PMID 35419003, 2022). "There is an evidence that IL-4 plays a critical role in allergic sensitization through the production of IgE and IgG1." (PMID 32063904, 2020). "Skin sensitization is primary associated with induction of Th1 cells, promoting a cytotoxic CD8+ T-cell response and secretion of IL-2 and interferon (IFN)-γ, while respiratory sensitization generally involve CD4+ Th2 cells and are characterized by high levels of IL-4, IL-10 and IL-13." (PMID 25760038, 2015).
skin infection (8 papers, 2013 to 2025). An inflammatory process affecting the skin, caused by bacteria, viruses, parasites, or fungi. "We showed previously that after repeated infection, M2-like dermal APCs conditioned within the skin infection site, which is rich in IL-4 and IL-10, were associated with decreased CD4+ T cell responsiveness in the skin draining lymph node." (PMID 25974019, 2015). "A recent study using a murine model of repeated exposures to schistosome cercariae prior to the onset of chronic egg deposition, revealed that the skin infection site becomes rich in Th2-associated IL-4, but also immune regulatory IL-10." (PMID 25974019, 2015). "Studies have shown that in humans and mice, IL-4 conditioning of neutrophils renders them ineffective during skin infection with Group A Streptococcus and during Listeria monocytogenes-induced sepsis." (PMID 38295799, 2024). "In S. aureus skin infections, both IL-4 and IL-23 (elevated in CC024) promote the production of IL-17." (PMID 39178306, 2024). "An association was confirmed between disease severity and transcription of the Th2 cytokines IL-4 and IL-13, and up-regulation of the Th17 cytokines IL-17 and IL-23 in pigs with crusted scabies." (PMID 25730203, 2015). "In addition, studies using skin infection models have demonstrated that eosinophil-derived IL-4 and IL-13 can sustain M2-like dermal resident macrophages and maintain skin barrier homeostasis, thereby limiting inflammation and promoting tissue repair." (PMID 41573250, 2025). "Additionally, a recent study demonstrated that basophil-derived IL-4 promoted S. aureus skin infection and IL-4 receptor blocking promoted enhanced bacterial clearance in a mouse model." (PMID 35007290, 2022).
Splenomegaly (8 papers, 2009 to 2026). Abnormal increased size of the spleen. "RELMα-deficient mice also exhibited IL-4 induced splenomegaly, which was more severe than observed in wild-type mice." (PMID 34349768, 2021). "Lmr15 detected in CcS-9 controls skin lesions, splenomegaly, hepatomegaly, and IL-4 and IgE in the serum, as well as parasite load in the lymph nodes and liver and eosinophil infiltration into the lymph nodes." (PMID 37600780, 2023). "IL-4 acts as both an inducing factor and an effector molecule of Tfh2 cells as IL-4 neutralization significantly decreased the frequencies of Tfh2 cells in SLE mice while alleviating splenomegaly and reducing IgE autoantibody titers in SLE mice." (PMID 35444658, 2022). "For instance, sustained IL-4 exposure leads to immunopathology such as the macrophage activation syndrome, where splenomegaly is observed." (PMID 34349768, 2021). "The STS allele of these markers was responsible for lower level of IFNγ and IL-4 in serum, but with larger splenomegaly and larger skin lesions." (PMID 31231359, 2019). "Lmr24 on chromosome 4 influenced splenomegaly, levels of IFNγ, and IL-4 in serum and development of skin lesions." (PMID 31231359, 2019). "Mann-Whitney post hoc analysis indicated that the level of circulating IL-4 was significantly higher in children who had splenomegaly, compared to children who had no organomegaly." (PMID 19149774, 2009). "Circulating levels of IL-4 were linearly related with the extent of spleen enlargement, as children with either moderate or substantial splenomegaly had significantly higher levels of circulating IL-4 than those who had no splenomegaly." (PMID 19149774, 2009).
steatosis (8 papers, 2011 to 2024). Increased lipid within the cytoplasm of cells. "Nevertheless, under insulin resistant status, the hepatic lipogenesis-promoting activity of IL-4 renders the liver more susceptible to develop steatosis by increasing FFA uptake and endogenous lipid synthesis." (PMID 30584465, 2018). "Therefore, although IL-4 exhibits positive regulatory effects to boost insulin efficacy, the energy deposit-promoting activity of IL-4 may make the liver more susceptible to develop steatosis under insulin resistant and diabetic models." (PMID 30584465, 2018). "Activated IL-17-secreting NKT cells were dominant in liver during the beginning of the steatosis phase, whereas IL-4/IL-13-secreting iNKT cells were prevalent later in the disease." (PMID 34440206, 2021). "We infer that under the status of consistent overnutrition, the excess circulatory FFAs released by peripheral tissues (such as adipose tissue due to the prolipolytic effect of IL-4) are transported to the liver to result in the consequence of steatosis." (PMID 30584465, 2018). "In conclusion, our study demonstrated association between hepatic expression of IL-4, IL-17, and CD163 with severity of HCV, being more expressed in moderate and marked grades of activity, late stages of fibrosis, and higher degrees of steatosis." (PMID 33906302, 2021). "Their concentration differences were statistically significant in comparison to patients with simple steatosis (IL-4 and IL-17) or to both groups of noncirrhosis NAFLD (IFNγ)." (PMID 38015590, 2023).